WRN (WRN RecQ like helicase)
Diseases named in the same sentence as WRN in open-access papers (continued):
Sharing a sentence is not in itself a finding about the gene and the disease.
cancer (continued). "Functional autosomal recessive loss of three members of the family BLM, WRN and RECQL4, results in hereditary human syndromes characterized by cancer predisposition and premature aging, but despite the finding that RECQL5 deficient mice are cancer prone, no such link has been made to human RECQL5." (PMID 27764811, 2016). "Our novel observations suggest that WRN abundance along with CPT-induced degradation could be a promising strategy for personalizing CPT-based cancer chemotherapeutic regimens." (PMID 26959889, 2016). "Interestingly, CPT-induced WRN degradation was confined to CPT-sensitive cancer cells suggesting a role for WRN in rendering resistance against CPT." (PMID 26959889, 2016). "Defects in WRN and BLM, which resemble DHX9 in their substrate specificities, lead to rare autosomal recessive disorders characterized by premature aging, growth retardation, increased genome instability, and increased cancer susceptibility." (PMID 27034008, 2016). "Thus, inherited loss of function mutations in fork repair enzymes like WRN and SMARCAL1 cause diseases that include an increased predisposition to cancer." (PMID 23671665, 2013). "Furthermore, WRN expression is thought to affect sensitivity to DNA topoisomerase I inhibitors in cancer therapy." (PMID 22797812, 2012). "This review focuses on the novel evidence of a functional relationship between WRN and the replication checkpoint and how this cross-talk might contribute to prevent genome instability, a common feature of senescent and cancer cells." (PMID 21389352, 2011). "As the mechanism of how WRN mutations lead to cancer in WS patients is still not entirely understood, researchers continue to pursue a better understanding of how these cancers evolve." (PMID 21267443, 2011). "Mutations in three of these helicase genes, RECQ2 (BLM), RECQ3 (WRN) and RECQL4, result in the rare autosomal recessive disorders of Bloom, Werner and RTS, which share the general characteristics of genomic instability and cancer predisposition." (PMID 20113479, 2010). "All three of these rare human diseases are characterized by a predisposition to cancer and chromosome instability, but the clinical features and cellular phenotypes are different from each other, suggesting unique roles of BLM, WRN, and RECQ4 helicases as tumor suppressors." (PMID 18074021, 2007). "Thus, downregulating WRN function may be a viable strategy in microsatellite unstable cancers, but this would depend upon their having many expanded TA repeat sequences in those cancers." (PMID 39125869, 2024). "Indeed, a small-molecule compound that inhibits WRN helicase activity, obtained by screening, sensitizes cancer cells to some DNA-damaging agents, including topoisomerase inhibitors, poly(ADP ribose) polymerase (PARP) inhibitors, and DNA cross-linking agents, as well as BRCA2-mutated cells." (PMID 36292687, 2022). "In this review, we will discuss ATR inhibitors, Polθ inhibitors and WRN inhibition as potential treatments for cancer and highlight how lessons from the discovery and development of PARPi and the study of PARPi resistance could inform the clinical development and use of new DDR inhibitors." (PMID 35567571, 2022). "Whilst this might be theoretically possible with WRN inhibitors in cancers with expanded TA repeats, approaches that target cancers with different types of mutational signature are not known but could be identified (an attempt to identify these is described here)." (PMID 35567571, 2022).
cancer (continued). "Interestingly, CPT treatment leads to the degradation of WRN, suggesting that cancers with microsatellite instability may be a candidate target for CPT treatment to drive WRN-specific vulnerable tumors." (PMID 33718381, 2021). "Thus, WRN is a promising target in cancers with microsatellite instability (MSI)." (PMID 32455893, 2020). "Defects of WRN, BLM and RECQL4 may increase cancer predisposition in humans." (PMID 31897211, 2020). "Therefore, inhibition of WRN function may represent a useful strategy to compromise rapidly dividing cancer cells dependent on WRN to deal with replicative lesions." (PMID 29998112, 2018). "This may be relevant to the development of WRN helicase inhibitors for anti-cancer therapy." (PMID 25906194, 2015). "A functional relationship seems to exist between WRN and the replication checkpoint in normal cells, but an inability of this crosstalk might contribute to induce genomic instability, a common feature in senescent cells and cancer cells." (PMID 25620975, 2014). "BLM, WRN, and RTS syndromes are recessive genetic disorders of humans caused by loss of function by BLM, WRN, and RTS helicases, respectively, and are characterized by genomic instability in patient cells, predisposition to various cancers and accelerated onset of aging phenotypes." (PMID 25620975, 2014). "However, a high WRN expression may possibly be a prerequisite to maintain genomic integrity in rapidly growing carcinoma cells in normal subjects." (PMID 25620975, 2014). "Werner syndrome helicase (WRN) is a RecQ-family DNA helicase essential for genome maintenance and is a synthetic lethal target in microsatellite instability-high (MSI-H) cancers." (PMID 41606312, 2026). "These clinical programs represent the first translation of WRN synthetic lethality to the clinic and are expected to clarify the therapeutic value of WRN targeting in MSI-H cancers, either alongside or after immunotherapy." (PMID 41190241, 2025). "Moreover, WRN-deficient cells exhibit defective DNA double-strand break (DSB) repair, an inability to resolve stalled replication forks, and an increased frequency of chromosomal aberrations, including deletions and translocations, which significantly heighten cancer risk in these individuals." (PMID 39958080, 2025). "WRN exonuclease conjugation to TDM/MSN further enhances fibrosis by eliminating ecDNA, offering a promising strategy for cancer treatment." (PMID 39206698, 2024). "We highlighted cancer type-specific genetic interactors, namely NDUFB5, MDM2, TUBA1B, and WRN, which were promising targets of existing and in-development drugs." (PMID 39578878, 2024). "For example, work we participated in as part of a Cancer Genome Pan-Cancer Atlas DDR (DNA Damage and Response) Working Group identified WRN as one of the Top 50 altered DDR genes among the >10,000 cancers included in the Pan Cancer Atlas cohort." (PMID 38994931, 2024). "Important endocrine system and cancer-related genes and pathways appear to be dysregulated among WTC-exposed individuals; these include WRN, BRCA1, NOTCH1, and NTRK1, among others." (PMID 38131903, 2023). "BLM, WRN, RECQL4, and RECQL5 were repressed by stromal and/or immune elements in most types of cancer, while RECQL exhibited reverse patterns." (PMID 37626815, 2023). "On the other hand, if MSI development occurs first followed by cancer evolution from an MSI clone, the entire cancer cell population would be MSI and, thereby, WRN dependent (bottom branch)." (PMID 36379964, 2022). "In this regard, we showed that a rapid induction of TOP1cc and its subsequent removal in WRN‐proficient cancer at nanomolar concentration of CPT, while this was abrogated in WRN‐KO cells, suggesting a key role of WRN in TOP1cc removal/repair." (PMID 35582959, 2022).
cancer (continued). "The synthetic lethal relationship between WRN and MSI has nurtured interest by academic groups and companies to develop WRN inhibitors to selectively target MSI cancers, with some drug development programmes already underway." (PMID 36379964, 2022). "Of note, consistent with published data that actively proliferating cancer cell lines display an elevated level of WRN45, we detected substantially enhanced WRN immunofluorescence in PCNA-positive cells as compared to PCNA-negative cells." (PMID 34772932, 2021). "DDR and related genes were found frequently methylated in human cancers, including BRCA1/2, MGMT, WRN, MLH1, CHFR, P16 and APC." (PMID 32974031, 2020). "CRISPR and RNAi-based studies verified that WRN is selectively essential MSI cell lines and dispensable in MSS cancer cell lines." (PMID 31591445, 2019). "Of those tested in cell-based assays, small molecule inhibitors of DNA unwinding catalyzed by WRN, BLM, and DNA2 all negatively affect proliferation of cancer cells and induce DNA damage and/or chromosomal instability." (PMID 29998112, 2018). "These include the role of WRN in DNA double-strand break (DSB) repair, telomere maintenance, senescence and heterochromatin stabilization, and cancer." (PMID 29043077, 2017). "In total 25 genes, including the WRN progeria gene, the MYC cancer gene and the longevity MTOR (also known as FRAP1) gene, were selected for replication analyses." (PMID 22247756, 2012). "WRN belongs to the RecQ family of helicases that has five human members including the BLM and RecQ4 proteins that are defective in the cancer-prone Bloom and Rothmund-Thomson syndromes, respectively." (PMID 16503984, 2006). "Interestingly, WRN and BRCA2 co-regulate replication fork stabilization in cancer cells and promote cell proliferation." (PMID 40649870, 2025). "Complementary approaches could also focus on γδ T cells, especially in MMRd cancers with MHCI defects 47, DCs 29,48, PD-1 and PI3K-γ expressing myeloid cells 49,50, the HLA-E and HLA-G molecules 20,35,51–56, WRN inhibitors 57 or TREM1 myeloid cells." (PMID 40027748, 2025). "When WRN nuclease activity is inhibited, MRE11 will cleave unprotected forks, generating mus81-dependent DSBs, while increasing NHEJ and chromosomal instability, leading to cancer cell death." (PMID 39759116, 2025). "Therefore, when WRN is inactivated, the “genomic scar” will be cleaved by MUS81 endonuclease, resulting in cancer cell death." (PMID 39759116, 2025). "Given the lack of WRN inhibitor response data in cancer patients harbouring KMT2DWT and KMT2DLOF tumours, the lack of a relationship between KMT2D status and WRN inhibitors in patient samples (e.g. biopsies) remains a limitation of our study." (PMID 39578878, 2024). "Multiple studies have demonstrated that cancer cells with microsatellite instability (MSI) are intolerant to loss of the Werner syndrome helicase (WRN), whereas microsatellite-stable (MSS) cancer cells are not." (PMID 39242638, 2024). "Furthermore, we used cancer patient data to provide evidence for KMT2DLOF alterations as a potential biomarker for ICI and WRN inhibitor treatments." (PMID 39578878, 2024). "Our findings serve as a proof-of-concept that a PROTAC approach could be a suitable alternative to WRN inhibition, addressing an unmet clinical need for the treatment of MSI cancers." (PMID 39242638, 2024). "We showed for the first time that MSI cell lines harbouring KMT2DLOF alterations were more sensitive to WRN KO than KMT2DWT MSI cell lines, contrary to the previous studies indicating that the MSI feature alone is sufficient for cancer cells to confer a survival vulnerability to WRN perturbation." (PMID 39578878, 2024). "The microsatellite unstable cancer cell lines showed a massive increase in double-strand breaks when WRN was not functional, leading to a substantial increase in cell death." (PMID 39125869, 2024).
cancer (continued). "It is noteworthy that our study was the first time that identified BLM, WRN, XPA, and RAD54L germline P/LP alterations in BTC patients, supporting consideration of expanded genetic testing for those with positive family cancer history or early-onset disease (below 45 years old)." (PMID 36072793, 2022). "In a joint analysis of MSI-prone cancer types (colorectal, ovary, stomach, uterus), we found links between the MMR SBS signatures that we inferred in the cell line exomes and the sensitivity to WRN knockout." (PMID 35614096, 2022). "We have determined the crystal structure of WRN helicase core, a highly anticipated structure due to the recently discovered importance of WRN as selective dependency of and therapeutic target in MSI cancer cells." (PMID 33199508, 2021). "However, several recent studies have identified WRN as a potent and selective vulnerability of microsatellite instability-high (MSI-H) cancers." (PMID 33199508, 2021). "In this regard, WRN plays an essential role in the survival of MSI/dMMR cancer cell lines (not in MMR-proficient and MSS cells)." (PMID 34164337, 2021). "Importantly, recent research revealed that WRN induced double-stranded DNA breaks and promoted apoptosis and cell cycle arrest selectively in MSI-H cancer models." (PMID 33525614, 2021). "WRN was the top dependency identified in a genome wide inactivation study and the helicase activity of WRN was demonstrated to be essential for survival of these cells but not related microsatellite stable cancer cells." (PMID 33095241, 2020). "Moreover, several other compounds targeting proteins involved in DNA repair mechanisms have already shown promising results as potential new anti-cancer drugs in pre-clinical studies, such as BLM, WRN, RAD52, or MRE11 inhibitors." (PMID 33036275, 2020). "WRN and BLM also appear to be involved in the alternative lengthening of telomeres (ALT) pathway, that is a telomerase independent pathway, that uses HR to lengthen telomeres and is frequently activated in cancer." (PMID 33095241, 2020). "Given the close relationship between the WRN and BLM helicases, and the fact that the silencing of both is used in the treatment of multiple forms of cancer, it stands to reason that certain shared pathways govern the link between these two proteins and cancer cell proliferation." (PMID 31210839, 2019). "Our study provides valuable information on RPA’s interactions with WRN and FANCJ helicases, which may be useful for developing therapeutic strategies for cancer treatment." (PMID 31570747, 2019). "Our study suggests that pharmacological inhibition of WRN helicase function represents an opportunity to develop a novel targeted therapy for MSI-H cancers." (PMID 30910006, 2019). "Because accelerated cell division imposed by activated MYC is associated with increased risk of replication errors and DNA damage, it is reasonable to postulate that cancer cells with activated MYC are particularly sensitive to reduced RecQ helicases such as BLM and WRN (59, –, 62)." (PMID 25477524, 2015). "Besides, we observed varying expression of APLF, BRCA1, WRN and LIGASE I in normal and cancer cells." (PMID 25789972, 2015). "Besides their biological importance in the prevention of tumorigenesis and accelerated aging, WRN and BLM are also new targets for cancer chemotherapy." (PMID 25400656, 2014). "Consistent with this hypothesis, cancer cells overexpressing MYC proteins are addicted to DNA helicase, WRN, which plays an important role in resolving replication stress." (PMID 24728180, 2014).
cancer (continued). "Given the genetic linkage of other human RecQ helicases (WRN, BLM, RECQ4) to diseases characterized by premature aging, cancer, and chromosomal instability, we investigated the significance of human RECQ1 for genome integrity, and more specifically its role in the DNA damage response." (PMID 18074021, 2007). "Furthermore, expanded cruciform-forming (AT)n repeats in MSI cancers are unwound by WRN; in the absence of WRN, these become substrates for MUS81-EME1/SLX1-SLX4 cleavage." (PMID 41370868, 2025). "Because MMR defects increase replication stress, WRN, a RecQ-family enzyme with both helicase and exonuclease, becomes critical for maintaining genome stability, creating a synthetic lethal requirement in MSI-H cancers while remaining largely dispensable in MSS contexts." (PMID 41190241, 2025). "In other words, our analysis indicated that WRN may be required for MSI cancer cell survival only when KMT2DLOF mutations are present and that MSI alone may not result in WRN dependence, in contrast to initial descriptions." (PMID 39578878, 2024). "Moreover, promising new small molecules targeting WRN and exhibiting synthetic lethality in dMMR/MSI cancers could be expected to work similarly efficient in our dMMR rhesus CRCs." (PMID 38504345, 2024). "Although WRN was categorised as a drug target group II candidate by the Open Target Platform, there are currently several drug development programs underway to target WRN in MSI cancer; therefore, we re-classified it as a drug target group I and priority class A gene." (PMID 39578878, 2024). "Since WRN‐depleted cancer cells or WS patient‐derived cells are highly sensitive to TOP1 inhibitors, we envisaged that WRN might be orchestrating TOP1cc removal and subsequent NF‐κB activation to offer therapeutic resistance in WRN‐proficient cells." (PMID 35582959, 2022). "Therefore, we tested the effects of WRN helicase inhibition on the survival of cancer cells lacking functional BRCA2." (PMID 34772932, 2021). "However, limited studies have investigated the role of WRN in developing cancer in non-WS individuals." (PMID 34164337, 2021). "WRN depletion causes DSBs and chromosome shattering and reduces the cell viability in MSI cells but neither in microsatellite stable (MSS) cancer cells nor in primary human cells." (PMID 33791310, 2021). "Thus, DNA repair helicases expressed highly in most malignant and rapidly proliferating cancer cells not only provide new proliferative protein markers, such as WRN and RECQL1 proteins, but also provide logical consequences for combination therapy to fight against drug-resistant cancer cells." (PMID 25620975, 2014). "In addition, we thoroughly validated the efficacy of WRN inhibitors in vivo, demonstrating their ability to selectively halt the growth of MSI tumors without causing toxicity, as they induce DNA damage only in cancer cells." (PMID 38587317, 2024). "While WRN is commonly regarded as a tumor suppressor, its pharmacological inhibition was proposed to achieve synthetic‐lethal effects in neoplastic cells characterized by high replication stress, which may render it effective also against MYC‐overexpressing cancer." (PMID 36214609, 2022). "However, in MSS cancer and non-transformed cells WRN depletion had no or very mild effects on viability, suggesting that pharmacological inhibition of WRN might allow for an MSI-H cancer-directed therapy that spares normal cells and tissues." (PMID 30910006, 2019). "However, determining how cells decide whether to undergo premature senescence or cancer in the absence of WRN requires additional experimental evidence." (PMID 30400178, 2018). "Similar to MSS cancer models, non-transformed telomerase-immortalized human retinal pigment epithelial cells (hTERT RPE-1) did not display sensitivity to knock-down of WRN." (PMID 30910006, 2019).
cancer (continued). "While J21 cells are a sub-clone of a cancer cell line (HT1080) with known defects in DNA repair genes (e.g. ERCC5, FANCC, MSH3, and WRN), hTERTs are an immortalized, non-cancerous cell line that does not contain any known defects." (PMID 25893404, 2015). "Genetic depletion of WRN was shown to lead to DNA damage, anti-proliferative effects, mitotic defects with cell cycle arrest, chromosome shattering and apoptosis in MSI cancer models, but not in cancer cells with an intact MMR pathway." (PMID 38658754, 2024).